IL11 (interleukin 11)
Diseases named in the same sentence as IL11 in open-access papers (continued):
Sharing a sentence is not in itself a finding about the gene and the disease.
hepatocellular carcinoma (19 papers, 2011 to 2026). A malignant tumor that arises from hepatocytes. "In our work, we identified YAP pathway is involved in IL-11-medidated transition of HSCs-to-myofibroblasts, which might not only be related to liver fibrosis, but also to the cancer-associated fibroblasts in hepatocellular carcinoma." (PMID 41362740, 2026). "In regarding to the downstream of TMED3 in tumor, a previous study proposed that TMED3 promoted metastasis of hepatocellular carcinoma and served as a contributor in tumor progression via IL-11/STAT3 signaling pathway." (PMID 35854294, 2022). "Of note, a long non-coding RNA activated by TGF-β (lncRNA-ATB) promotes organ colonization of disseminated hepatocellular carcinoma cells by binding the IL-11 mRNA and the autocrine induction of IL-11 expression." (PMID 34201209, 2021). "Yuan reported that the lncRNA ATB bound to IL-11 mRNA and increased IL-11 mRNA stability and secretion in hepatocellular carcinoma." (PMID 30034397, 2018). "TMED3-mediated IL-11/STAT3 signaling pathway activation was recently reported to participate in tumor progression in hepatocellular carcinoma." (PMID 29100303, 2017). "These two case reports also demonstrate that patients with hepatic carcinoma who experience this rare form of CLS after treatment with IL-11 seem to respond to a therapeutic regimen that involves hydroxyethyl starch, albumin, and diuretic therapy." (PMID 21619578, 2011). "Case 1 was a 46-year-old man with recurrence of hepatic carcinoma who was treated with IL-11 (3 mg per day)." (PMID 21619578, 2011). "YTHDF2 silencing provoked tumor-promoting inflammation, vascular reconstruction, and energy metabolism reprogramming in hepatocellular carcinoma by inhibiting the degradation of m6A-modified IL11 (interleukin 11) and SERPINE2 (serpin family E member 2) transcripts." (PMID 37028765, 2023). "In addition, YTHDF2 inhibits the normalization of tumor vasculature in hepatocellular carcinoma cells by increasing the attenuation of IL11 and SERPINE2 mRNAs." (PMID 35572524, 2022). "In addition, lncRNA-ATB promotes organ colonization of disseminated hepatocellular carcinoma cells by binding to IL-11 mRNA and subsequently activating IL-11/STAT3 signaling." (PMID 28671581, 2017). "In a study on hepatocellular carcinoma (HCC), IL-11 was shown to promote tumor cell proliferation and resistance to apoptosis by activating the STAT3 signaling pathway, contributing to cancer recurrence in postoperative HCC patients." (PMID 39421736, 2024). "In addition, reducing YTHDF2 reduced m6A-containing IL11 and SERPINE2 mRNA in hepatocellular carcinoma to aggravate inflammation and vascular abnormalities." (PMID 33505426, 2020). "OPN and BSP are particularly helpful for assessing bone metastases in lung and prostate cancers, whereas other markers such as CTGF, IL-11, and MMP-1 have demonstrated greater prognostic significance in hepatocellular carcinoma (HCC)." (PMID 40426987, 2025). "Notably, the benefit of focused short-term application of IL-11 or IL-22 in acute disorders, such as APAP-induced ALI, should likely outweigh the inherent danger of these cytokines to promote in the long run tumor growth, which has been detected for IL-22 and hepatocellular carcinoma patients." (PMID 27199988, 2016). "A direct correlation between IL-11 and CLS has never been reported previously, particularly in patients with hepatic carcinoma." (PMID 21619578, 2011).
liver fibrosis (19 papers, 2020 to 2026). "However, recent studies have questioned earlier assumptions as IL11 appears to cause hepatic fibrosis, steatosis, and inflammation in a number of liver diseases." (PMID 35806094, 2022). "Considering the activated HSCs featured by the acquiring abilities to contract/migrate and the increase of collagen synthesis are the central drivers to lead to liver fibrosis 10, the role of IL-11 in HSCs during this process was our concern." (PMID 41362740, 2026). "Overall, our work elucidates that IL-11 is a critical factor to induce liver fibrosis by activating HSCs through GP130-SFK-YAP pathway, and promoting fibrogenesis by inducing TGF-β and chemokines expression through the M2-like phenotypic change of macrophage." (PMID 41362740, 2026). "In our work, HSCs intrinsic IL-11 is proved to be a hazardous determinant in the pathological progression of hepatic fibrosis." (PMID 41362740, 2026). "As reported, blockade of IL-11 signaling in diet-induced MAFLD mouse model can relieve liver fibrosis 17, 18, we evaluated the benefit of IL-11 nanobody on the CCl4-induced liver injury to further highlight the potent role of IL-11 in fibrogenesis." (PMID 41362740, 2026). "AAV6-mediated IL-11 overexpression in the HSCs aggravated hepatic fibrosis induced by CCl4 in C57/B6 mice, accompanied by a marked increase of M2 macrophages." (PMID 41362740, 2026). "Previous studies have shown that IL11 released from hepatocytes plays an important role in the development of liver fibrosis." (PMID 40789837, 2025). "Previous studies have demonstrated that IL11 released by hepatocytes is a critical factor in the progression of liver fibrosis." (PMID 40789837, 2025). "Detrimental effects of high IL-11 concentrations have also been evidenced in a liver fibrosis model, where injection of mouse recombinant IL-11 into mice induces liver damage characterized by fibrosis, inflammation, and cell death." (PMID 38732588, 2024). "Corroborating the cardiac findings, in a model of nonalcoholic steatohepatitis, IL-11 inhibition by X203 or X209 decreased liver fibrosis by suppressing ERK activation and consequently MMP2 and TIMP1." (PMID 38392279, 2024). "IL-11 is a member of IL-6-like cytokines and has recently gained more attention in both cardiac and liver fibrosis but also in vascular remodeling." (PMID 35626694, 2022). "We suggest that inhibiting IL11 signaling in hepatocytes targets an initiating nexus for diet-induced steatohepatitis that impacts subsequent liver fibrosis and inflammation." (PMID 33397952, 2021). "To explore whether MCM7 promotes liver fibrosis through IL11 in vivo, we administered rhIL11 to inhibit endogenous IL11 activity in mouse models subjected to S. japonicum infection or chronic CCl4 treatment." (PMID 40789837, 2025). "The involvement of MCM7 in this regulatory pathway unveils a novel mechanism by which MCM7 modulates IL11 expression, a process that may critically influence liver fibrosis progression and potentially other pathological conditions." (PMID 40789837, 2025). "IL11 levels correlate with liver fibrosis severity and promote HSC activation." (PMID 40789837, 2025). "Additionally, recombinant human IL11 (rhIL11), which effectively inhibits endogenous IL11 signaling, significantly attenuated the exacerbation of liver fibrosis driven by MCM7 overexpression in vivo." (PMID 40789837, 2025). "A research team also constructed NP-AEAA-coated siRNA (si@NP-AEAA) using nanoparticle NP-AEAA, which is predominantly target-enriched in aHSCs, to regulate HSC activation and fibrotic remodeling by blocking IL-11/ERK signaling in a mouse model of hepatic fibrosis’ increased IL-11 expression." (PMID 40362316, 2025). "Interestingly, we found that IL11 expression was elevated in liver tissues and hepatocytes during liver fibrosis induced by S. japonicum or CCl4." (PMID 40789837, 2025).
liver fibrosis (continued). "Previous studies have also proven that the activation (phosphorylation) of ERK and the expression of fibrosis markers are inhibited by inhibiting IL-11, which reduces hepatocyte death and liver fibrosis, inflammation, and steatosis in non-alcoholic steatohepatitis models." (PMID 36277879, 2022). "Both serum TGF-β and hepatic CCLs rose up in IL-11 overexpression group could be alleviated by macrophage depletion in vivo, which suggested macrophage as a potent paracrine target of IL-11-faciliated liver fibrosis, except for the autocrine effect of IL-11 on HSCs." (PMID 41362740, 2026). "This activation leads to transcriptional upregulation of IL11, which further promotes HSC activation and ultimately drives liver fibrosis progression." (PMID 40789837, 2025). "In conclusion, our findings demonstrate that MCM7 enhances hepatocyte-derived IL11 production, which drives HSC activation and promotes liver fibrosis progression." (PMID 40789837, 2025). "Mechanistically, our findings demonstrated that MCM7 activates IL11 expression via the SHCBP1-RACGAP1-STAT3 signaling pathway, thereby promoting the hepatic stellate cell activation and driving liver fibrosis progression." (PMID 40789837, 2025). "This interaction between MCM7 and SHCBP1 regulates IL11 expression through the RACGAP1-STAT3 pathway, underscoring a novel mechanism for liver fibrosis progression." (PMID 40789837, 2025). "In other indications, IL-11 also induces fibrosis and inflammation via ERK-dependent pathways, such as in liver fibrosis and idiopathic pulmonary fibrosis, thereby confirming its actions in the pathogenesis of multiple diseases." (PMID 35626694, 2022). "Even though IL-11 is a cytokine, its role on immune microenvironment during the deterioration of liver fibrosis has not been fully elucidated." (PMID 41362740, 2026). "As Il11, a master regulator of fibrosis, was strongly induced by S. mansoni infection and further boosted by inhibition of JNK, we assessed the extent of hepatic fibrosis and the activation of hepatic stellate cells." (PMID 40751475, 2025). "Inhibiting IL11 signaling reduces hepatocyte death, liver fibrosis, inflammation, and steatosis in murine models of non-alcoholic steatohepatitis." (PMID 40789837, 2025). "Given that hepatic MCM7 activates IL11 transcription and IL11 promotes HSC activation, we hypothesized that MCM7 accelerates liver fibrosis by inducing IL11 release, which subsequently activates HSCs." (PMID 40789837, 2025). "Moreover, IL11 and NOX4 in particular are critically involved in mediating downstream TGF-β effects in cardiovascular and liver fibrosis as well as systemic sclerosis." (PMID 33440877, 2021).
asthma (16 papers, 2012 to 2025). "IL-11 modulates airway remodeling in individuals with asthma by promoting airway fibrosis and inhibiting alveolar development." (PMID 38352248, 2023). "IL11 is selectively expressed in eosinophils and epithelial cells in patients with moderate and severe asthma, and correlates directly with disease severity." (PMID 35628459, 2022). "IL-11 is highly expressed as a consequence of viral induced asthma, and overexpression of IL-11 in the airways of mice results in remodeling of the airways, inflammation and asthma-like symptoms." (PMID 32765502, 2020). "In other Th2-dominant inflammatory diseases, like asthma, the high level of IL-11 has been measured." (PMID 29914371, 2018). "This is probably because certain types of respiratory viruses help to produce more interleukin-11 (IL-11), which exacerbates asthma from pulmonary stromal cells." (PMID 25032810, 2014). "Asthma is a common chronic inflammatory disease of the airways and IL-11 and IL17F are considered as critical cytokines in the pathogenesis of airway inflammation." (PMID 24705157, 2013). "Rhinoviruses infection promotes the secretion of cytokines from epithelial cells, such as IL-6, IL-8, IL-11, and GM-CSF, which may trigger the onset of asthma." (PMID 38904891, 2025). "Similarly, fibroblast-derived IL6, IL8, and IL11 have been shown to activate and attract neutrophils during neutrophil inflammation in asthma but also to activate T-cells by increasing CD40L expression." (PMID 37497214, 2023). "Consistent with previous studies on other autoimmune diseases, such as multiple sclerosis, rheumatoid arthritis, and severe asthma, our data demonstrated that circulating IL-11 was overexpressed in TAO patients than in healthy controls and was correlated positively with disease activity." (PMID 35273577, 2022). "IL-11 has been shown to play an anti-inflammatory role in the airways and asthma." (PMID 22715999, 2012). "Interestingly, IL-17 is upregulated in asthma as eosinophils are cellular sources of its production, and IL-17 increases synthesis of IL-6 and IL-11 by bronchial fibroblasts derived from bronchial biopsies of asthmatic subjects." (PMID 22203879, 2012). "Although IL11 is upregulated in systemic sclerosis, TNF-resistant ulcerative colitis and asthma and despite SMCs being a source of IL11, the effect of IL11 function in SMC biology has not been studied." (PMID 31917819, 2020). "In the same way as IL11 enhances the disease severity in asthma, overexpression of IL6 and IL11 in Asp may reflect the severity of IL6-mediated inflammation and type 2 inflammation enhancing the disease severity in CRS." (PMID 35628459, 2022). "Subsequent studies have shown that IL-11 signaling is critical for a TH2-mediated inflammatory response in the lung, and that inhibition of IL-11 signaling in the lung alleviates inflammation, implying that IL-11 signaling is a therapeutic target in asthma." (PMID 32765502, 2020).
rheumatoid arthritis (16 papers, 2018 to 2026). A chronic, systemic autoimmune disorder characterized by inflammation in the synovial membranes and articular surfaces. "In pathological circumstances, illnesses like osteoarthritis and rheumatoid arthritis (RA) are intimately linked to bone loss due to aberrant IL-11 expression." (PMID 40873591, 2025). "In rheumatoid arthritis (RA), a chronic immunological disease with bone destruction and synovitis, an association was observed between IL-11 expression and osteoarthritis." (PMID 38352248, 2023). "In the context of rheumatoid arthritis and diabetic eye disease, IL11 secreted from fibroblasts causes EndoMT and this is linked with neo-angiogenesis." (PMID 38054591, 2023). "In rheumatoid arthritis, IL-11 promotes the migration of fibroblasts to the joints and the secretion of cytokines." (PMID 37304948, 2023). "Owing to its pivotal role in inflammatory conditions, IL-11 has been investigated as a therapeutic candidate for rheumatoid arthritis, Crohn’s disease, refractory immune thrombocytopenic purpura, and periodontal disease." (PMID 33562198, 2021). "Dysregulation of IL-6 and IL-11 signaling contributes to several diseases, such as inflammatory bowel disease, osteoporosis, rheumatoid arthritis, and various types of cancer." (PMID 30197757, 2018). "This inhibition of interleukins, such as IL-11, may be crucial in maintaining the inflammatory state in nasal polyps, as IL-11 has been shown to attenuate inflammation in diseases such as rheumatoid arthritis or inflammatory bowel diseases." (PMID 37176721, 2023). "Interestingly, IL11 was reported to facilitate fibrosis and inflammation in cardiovascular fibrosis and rheumatoid arthritis." (PMID 37626330, 2023). "In rheumatoid arthritis, FasL affects the expression of IL-11 in fibroblast-like synovial cells." (PMID 38352248, 2023). "Since these pathways have also been associated with FAP+IL11+ FB in the LP and with FAP+ FB that accumulate in rheumatoid arthritis and tumor microenvironments, we hypothesize that such changes in TRC are, at least in part, a general response of FB to chronic inflammation." (PMID 41379085, 2026). "Other studies have shown that in rheumatoid arthritis (RA), IL-11 combined with IL-11RA in the endothelial cell directly activates RA angiogenesis." (PMID 37304948, 2023). "In summary, IL-11 can induce osteoclast formation through Jak/STAT pathway, MAPK/PI3K pathway, phosphorylation of Yes-associated protein 1 (YAP1) and RANKL-independent mechanism, and is associated with rheumatoid arthritis, femoral arthritis, osteoporosis and other bone diseases." (PMID 38352248, 2023). "In rheumatoid arthritis (RA), IL-11 is elevated in synovial membranes, synovial fluid, and the blood, but was initially thought to be cytoprotective and anti-inflammatory based on the effects of rhIL11 in both human cells and in a mouse model of arthritis." (PMID 38054591, 2023). "One study showed that IL-11 and IL-11Rα are co-expressed in rheumatoid arthritis synovitis fluid fibroblasts and endothelial cells and thus interconnect the function of these two cell types, whereas macrophages are not IL-11 responder cells because of no IL-11Rα expression." (PMID 30197757, 2018).
fibrosis (15 papers, 2020 to 2025). the formation of excess fibrous connective tissue in an organ or tissue in a reparative or reactive process. "For instance, fibroblast-specific IL11 transgene expression causes heart and kidney fibrosis and organ failure, whereas the genetic deletion of the interleukin 11 receptor alpha chain 1 protects against disease." (PMID 37892923, 2023). "IL-11 has been implicated in fibrosis of the heart, liver, and lung." (PMID 32765502, 2020). "Similar results were also reported by Cong and colleagues, in which Ang II treatment fostered IL-11 expression and α-SMA intensity, while treatment with IL-11 antagonist reduced α-SMA-positive myofibroblasts in atrial tissue from the fibrosis mouse model." (PMID 40092733, 2025). "In this study, we observed that IL-11 was upregulated in Ang-II-induced atrial fibroblasts, consistent with results from persistent atrial fibrillation patients and Ang II-treated fibrosis mouse models." (PMID 40092733, 2025). "Our studies on il11aOE in uninjured hearts demonstrated dual roles of il11a, acting as a double-edged sword in heart repair: il11 signaling can promote the regenerative program while also contributing to cardiac fibrosis." (PMID 39516197, 2024). "Bleomycin-induced fibrosis mouse model also demonstrated the increased level of IL-11 in serum and ERK1/2 phosphorylation in the skin." (PMID 36810081, 2023). "We suggest that myocardial stress signals that occur due to ischaemia or pressure overload result in the secretion of IL11 from cardiomyocytes, leading to cardiac fibrosis and inflammation." (PMID 37629170, 2023). "Expression of TGFβ1, IL-11 and IL-6, mediators involved in cardiovascular fibrosis and inflammation, were increased in hearts from TRPM7-deficient mice and aldosterone-salt treated WT mice." (PMID 35882956, 2022). "Numerous studies have established IL11 as a pivotal mediator of organ fibrosis and dysfunction." (PMID 40789837, 2025). "In rodents, Il11 roles on cardiac fibrosis have been reported, but its regenerative roles remain unclear." (PMID 39516197, 2024). "IL11 may therefore represent an alternative target, as its effects on cardiac fibrosis appear more profound than TGFβ, and IL11 is also proinflammatory." (PMID 37629170, 2023). "Given the direct link between TGF-β/Smad signaling and IL-11/ERK1/2 signaling pathway, we have verified that osthole has a direct inhibitory effect on IL-11/ERK1/2 signaling independent of TGF-β signaling by using an IL-11-induced HK-2 cells fibrosis model." (PMID 34054526, 2021). "IL11 was recently identified as a critical regulator of the TGFβ pathway and cardiac fibrosis: in the absence of IL11 activity, TGFβ cannot exert a profibrotic effect on human cardiac fibroblasts." (PMID 32955172, 2020).